SFTPC (surfactant protein C)
Diseases named in the same sentence as SFTPC in open-access papers (continued):
Sharing a sentence is not in itself a finding about the gene and the disease.
lung disease (17 papers, 2005 to 2025). "Surfactant protein-C deficiency is a rare lung disease characterized by a highly variable age of onset, severity of symptoms, and prognosis." (PMID 40575365, 2025). "Variants of the SFTPC gene are associated with severe, fatal neonatal lung disease and ILD in older children (surfactant, pulmonary-associated protein C; SFTPC—OMIM 178620)." (PMID 39457702, 2024). "Lung disease caused by different SFTPC mutations varies greatly, from respiratory distress syndrome (RDS) in neonates to ILD in adults." (PMID 31462320, 2019). "It was reported that heterozygosity for ABCA3 (another gene responsible for surfactant dysfunction) mutations modifies the severity of lung disease in individuals with the same SFTPC mutation suggesting modifier genes may be involved." (PMID 31462320, 2019). "Similarly, the role of surfactant protein C in ILD is reviewed and a model of surfactant protein C associated lung disease is described." (PMID 15819986, 2005). "SFTPC gene mutations may be an important risk factor for the development of common lung diseases." (PMID 34918679, 2021). "In mouse models, abnormal expression of genes specifically expressed in the respiratory system, such as surfactant protein C (SFTPC) deficiency and mucin 5B (MUC5B) overexpression, can also cause spontaneous lung diseases similar to clinical phenotypes." (PMID 38405059, 2024). "Both gene addition and gene editing strategies are compared to best design treatments for lung diseases resulting from pathogenic variants in the SFTPB, SFTPC, and ABCA3 genes." (PMID 35098209, 2021). "Several genetic variants have been identified for SFTPA1, SFTPA2, SFTPB, SFTPC, and SFTPD that are associated with pulmonary diseases." (PMID 33469544, 2020). "The molecular pathogenesis of SP-C related lung disease includes loss of gene expression without defined mutations, decreased expression from non-coding promoter mutations, and most commonly mutations in the SP-C coding gene (SFTPC)." (PMID 23399055, 2013).
lung adenocarcinoma (14 papers, 2012 to 2024). A carcinoma that arises from the lung and is characterized by the presence of malignant glandular epithelial cells. "Recent experiments have established that the expression of SFTPC was downregulated in human lung adenocarcinoma tissues and it was correlated with poor overall survival of ADC patients." (PMID 31877723, 2019). "The mouse Fat3 mRNA is significantly downregulated in lung adenocarcinoma occurred in transgenic mice expressing wild-type Raf1 transgene under the control of the human SP-C (surfactant protein C) promoter." (PMID 23076869, 2012). "This subset of patients is distinguishable clinically by earlier-onset disease in young adults associated with surfactant protein C (SFTPC) mutations and a history of lung adenocarcinoma being associated with surfactant protein A1 and A2 (SFTPA1 and SFTPA2) mutations." (PMID 35532056, 2022). "Moreover, SFTPC knockdown promotes lung adenocarcinoma progression." (PMID 33170151, 2020). "It was also revealed that miR-629-3p-induced surfactant protein C (SFTPC) downregulation promoted cell proliferation and predicted poor survival in lung adenocarcinoma." (PMID 32244823, 2020). "SGB1A1, SFTPC, and HOPX are all correlated with better survival in lung adenocarcinoma, while our results showed a reduction in mRNA of such markers in most of the cells." (PMID 32987632, 2020). "Pre-invasive lesions and tumours expressed the LUSC markers KRT5 and P63 and lacked expression of the lung adenocarcinoma (LUAD) marker surfactant protein C (SPC)." (PMID 34385275, 2022). "In fact, multifocal lung adenocarcinomas with AAH and BAC (lepidic) patterns develop at 3 to 5 weeks of age in transgenic mice expressing the del E748-A752 mutant version of mouse EGFR driven by the surfactant protein C promoter." (PMID 26422230, 2015).
COVID-19 (7 papers, 2020 to 2025). A disease caused by infection with severe acute respiratory syndrome coronavirus 2. "SFTPC, the encoding gene for pulmonary-associated surfactant protein C, emerged as a key identifier of COVID-19 patients with high viral load." (PMID 35326463, 2022). "Notably, SFTPC expression was ~49-fold higher in mild cases compared to asymptomatic COVID-19-positive patients (p < 0.0001), but then decreased by ~54-fold in severe cases relative to mild (p < 0.0001), returning to near-baseline levels." (PMID 40647689, 2025). "A prospective observational cohort study revealed that autoimmunity in severe COVID-19 patients is mediated through binding of immunoglobulin A (IgA) antibodies to human surfactant protein B (SP-B) and surfactant protein C (SP-C) leading to reduced levels of pulmonary surfactant." (PMID 34267664, 2021). "This study aimed to elucidate the effect of COVID-19 on the lung’s surface tension regulatory system by examining the expression of surfactant protein genes (SFTPA1, SFTPA2, SFTPB, SFTPC, and SFTPD) across different disease severity groups." (PMID 40647689, 2025). "In this study, we compared the expression of SFTPA1, SFTPA2, SFTPB, SFTPC, and SFTPD in blood among asymptomatic, mild, and severe COVID-19 patients to identify patterns related to disease severity." (PMID 40647689, 2025). "Other two surfactant proteins (SFTPC and SFTPD) were expressed at remarkably low levels in the COVID-19 lungs, indicating diminished expression of all four surfactant proteins in lungs in response to SARS-CoV-2 infection." (PMID 33060566, 2020). "But in COVID-19-affected lung, TTF1 and SFTPC genes were found to be downregulated, whereas SFTPB was upregulated." (PMID 33173052, 2020). "In a cohort of deceased COVID-19 patients, we observed by H&E that gas-exchanging flattened AT1 pneumocytes are virtually replaced by cuboidal cells that were subsequently confirmed to be AT2-like cells via immunofluorescent staining with the AT2-specific marker, surfactant protein C (SFTPC)." (PMID 34463615, 2021).
idiopathic pulmonary fibrosis (7 papers, 2011 to 2024). Idiopathic pulmonary fibrosis (IPF) is a nonneoplastic pulmonary disease that is characterized by the formation of scar tissue within the lungs in the absence of any known cause. "Sequence variants in genes for surfactant proteins (SFTPC, SFTPA1, SFTPA2, ABCA3), polymorphisms in MUC5B or TOLLIP, and mutations in telomere genes (TERT, TERC, PARN, and RTEL1) are associated with an increased risk of idiopathic pulmonary fibrosis (IPF)." (PMID 36864460, 2023).
acute respiratory failure (5 papers, 2010 to 2024). Life-threatening respiratory failure that develops rapidly. "In another study comparing children with acute respiratory failure and healthy newborn controls, SNPs in SFTPA1, SFTPA2, and SFTPC were associated with acute respiratory failure and pulmonary dysfunction after hospital discharge." (PMID 35913450, 2022). "The phenotype associated with SFTPC mutations is extremely heterogeneous leading from neonatal fatal respiratory failure to children and adults chronic respiratory disease with ILD." (PMID 20727133, 2010). "Pathogenic variants in this gene give rise to a rare form of progressive respiratory failure, which is linked to changes in surfactant production, structure, and balance, influencing the expression of associated genes, including SFTPB, SFTPC, and ABCA3." (PMID 38203821, 2024). "Synthetic surfactant based on recombinant surfactant protein C (SP-C) improves lung function in animal models of acute respiratory failure." (PMID 31694668, 2019).
fibrosis (5 papers, 2020 to 2025). the formation of excess fibrous connective tissue in an organ or tissue in a reparative or reactive process. "Models using silica, fluorescein isothiocyanate (FITC), radiation, or viral-based transgenes simulate occupational silicosis-related fibrosis, radiation pneumonitis, and genetic PF (e.g., Sftpc mutations encoding surfactant protein C), respectively." (PMID 40746422, 2025). "Certain mutations, particularly in SFTPB, are associated with lethal neonatal respiratory distress, whereas others, such as SFTPC mutations, may present later in childhood with a broader range of phenotypes, including interstitial pneumonitis, fibrosis, or restrictive lung disease." (PMID 41303225, 2025). "Moreover, our investigation demonstrates that a mutation at position 123 of the SFTPC gene, situated within the BRICHOS domain in whales, induces an upregulation of the lung fibrosis marker proteins MMP7 and α-SMA." (PMID 38575860, 2024).
Interstitial pneumonitis (5 papers, 2015 to 2025). "Familial interstitial pneumonia (FIP), a class of interstitial pneumonitis that may be caused by the genetic mutation in surfactant protein C (SPC), suggests a potential connection between organ fibrosis and ER stress." (PMID 34445377, 2021).
respiratory distress syndrome (5 papers, 2015 to 2024). "Surfactant protein C (SFTPC) gene mutations result in chronic interstitial lung disease in adults or severe neonatal respiratory distress syndrome." (PMID 32195974, 2020). "We present an extremely low birth weight male infant with an unusual course of respiratory distress syndrome associated with two mutations in the SFTPC gene: C43-7G>A and 12T>A." (PMID 26000190, 2015). "Surfactant protein C (SP-C) deficiency is associated with variable clinical manifestations ranging from neonatal respiratory distress syndrome to lethal lung disease." (PMID 26000190, 2015).
emphysema (4 papers, 2018 to 2024). "In the analysis using a transgenic mouse that expresses TNFα in alveolar type II cells under the control of the human surfactant protein C promoter, the overexpression of TNFα resulted in the development of pulmonary emphysema by the activation of the elastase." (PMID 37454739, 2023). "Importantly, AT2 cells of TRPV4-/- mice showed a decreased production of pro-surfactant protein C, a precursor of surfactant protein-C (SP-C), secreted from these cells and older mice exhibited emphysema-like changes in their lung structure." (PMID 33917551, 2021). "The finding that our model does not progress to a fibrotic or emphysema-like phenotype contrasts with studies performed in mice overexpressing TNF driven from the surfactant protein C promoter (SP-C/TNF-Tg) restricting expression to the lung." (PMID 29320550, 2018). "In a rat model of emphysema induced by cigarette smoke extract (CSE) and intratracheal lipopolysaccharide (LPS) instillation, the expression levels of Surfactant Protein A (SPA) and Surfactant Protein C (SPC) in lung tissues were found to be reduced, indicating damage to AECII." (PMID 38448466, 2024).
asthma (3 papers, 2012 to 2024). "Lung expression of surfactant protein genes SFTPA (P = 0.048) and SFTPB (P < 0.001), but not SFTPC (P = 0.177) or SFTPD (P = 0.285), was higher in lambs from asthma+beta than those from asthma ewes." (PMID 39436639, 2024).
cystic fibrosis (3 papers, 2018 to 2022). Autosomal recessive disorder caused by pathogenic variants in the CFTR gene (cystic fibrosis transmembrane conductance regulator), which encodes a chloride and bicarbonate channel expressed in epithelial cells, and follow the diagnosis criteria. "In cystic fibrosis, the genetic contribution of the surfactant protein genes, SFTPB, SFTPC, and SFTPD are contained." (PMID 36203529, 2022).
viral infection (3 papers, 2018 to 2025). "Mutations in surfactant protein C, viral infections, reactive oxygen species (ROS) generated by cigarette smoke or inhaled particulates and abnormal or reduced clearance of misfolded and damaged proteins have been identified as ER stress inducing factors in this disease." (PMID 30147026, 2018).
adenoma (2 papers, 2001 to 2022). A neoplasm arising from the epithelium. "Genetically modified mouse model demonstrated that not all KRAS-mutant lung cells equally developed to adenomas and malignant adenocarcinomas and only those derived from surfactant protein C + alveolar type II cells may progress to IVA." (PMID 36059824, 2022).
breast carcinoma (2 papers, 2020 to 2021). "CK-5 and P63 were picked because they are both markers of squamous cell carcinoma, and SFTPC, SCGB1A1, and HOPX are markers of LUAD, while CDH1 was picked because SLFN12 has been demonstrated to modulate CDH1 expression in prostate and breast cancers." (PMID 32987632, 2020). "Indeed, small‐EVs from breast cancer MDA‐MB231 sub‐cell line (4175) localized to the lungs following IV (retro‐orbital) administration with uptake by S100A4+ fibroblasts and surfactant protein C+ epithelial cells." (PMID 34194679, 2021).
non-small cell lung carcinoma (2 papers, 2021 to 2024). A group of at least three distinct histological types of lung cancer, including non-small cell squamous cell carcinoma, adenocarcinoma, and large cell carcinoma. "The human surfactant protein C promoter helps to regulate the expression of Fat3, and its expression is downregulated in non-small cell lung cancer." (PMID 34070222, 2021).
protein deficiency (2 papers, 2010 to 2017). "Several histological and clinical subtypes of ILD are linked to the SP-C protein deficiency caused by mutations of the corresponding SFTPC gene." (PMID 21092132, 2010).
brain-lung-thyroid syndrome (1 paper, 2020). Brain-lung-thyroid syndrome is a rare disorder characterized by congenital hypothyroidism (CH), infant respiratory distress syndrome (IRDS) and benign hereditary chorea (BHC). "This is the first report of brain-lung-thyroid syndrome concomitant with SFTPC mutation, which caused severe ILD and persistent low oxyhemoglobin saturation, which caused the patient's death." (PMID 32195974, 2020).
diabetes (1 paper, 2023). "Our RNA-seq data showed PP1MB and SFTPC as common in PCa and diabetes." (PMID 38235353, 2023). "While FOXP1 was found to be a common interaction partner of PP1MB, SFTPC and TMEM67, an intriguing finding was that the BLM gene was the only common gene among PCa, diabetes mellitus, and obesity, interacting with both FOXP1 and TMPO." (PMID 38235353, 2023).
Failure to thrive (1 paper, 2019). Failure to thrive (FTT) refers to a child whose physical growth is substantially below the norm. "Our study showed an earlier age of onset and a more prevalent failure to thrive in group with SFTPC mutations." (PMID 31462320, 2019).
gastric adenocarcinoma (1 paper, 2024). "We have previously reported that gastric adenocarcinoma of the fundic gland type shows high expression levels of SFTPB and SFTPC, both of which are transactivated by the ectopic expression of NKX2-1/TTF1." (PMID 37962678, 2024).
Granuloma (1 paper, 2024). A compact, organized collection of mature mononuclear phagocytes, which may be but is not necessarily accompanied by accessory features such as necrosis. "It is known that SFTPC and SFTPB are characteristic genes of alveolar epithelium, representing the normal lung tissue component involved in the heterogeneity of tuberculosis granulomas." (PMID 39431015, 2024).
lymph node metastasis (1 paper, 2024). "Unfortunately, the low expression of SFTPC had no obvious relationship with age, gender, T stage and lymph node metastasis in our collected 45 pairs of LUAD samples." (PMID 39346732, 2024).
pulmonary adenomas (1 paper, 2023). "Surfactant protein C (SPC) promoter-directed overexpression of prostacyclin synthase (PGIS) in mice prevents the development of pulmonary adenomas in several chemical carcinogenesis models, including urethane, 3-methyl cholanthrene/butylated hydroxytoluene, and tobacco smoke." (PMID 37711198, 2023).
pulmonary alveolar proteinosis (1 paper, 2011). A rare lung disorder characterized by the filling of the pulmonary alveoli with proteinaceous material which stains positive with periodic acid-Schiff stain. "Similarly, a study of lung surfactant protein C (SP-C), whose amyloid fibril formation is related to pulmonary alveolar proteinosis, showed that substitutions of leucines for valines in an α-helix/β-strand discordant region increase the helical content and reduce amyloid fibril formation." (PMID 21408230, 2011).
pulmonary hypertension (1 paper, 2022). Increased pressure within the pulmonary circulation due to lung or heart disorder. "For example, chronic production of TGF-α in surfactant protein-C (SP-C)-expressing cells disrupted alveolar and vascular development and caused pulmonary fibrosis and pulmonary hypertension in mice." (PMID 35326439, 2022).
respiratory infections (1 paper, 2024). "However, interactions with other variants (for example, variants of SFTPB or SFTPC) or with external, environmental factors (for example, respiratory infections or smoking) may induce changes in the phenotype." (PMID 39457702, 2024).
Respiratory insufficiency (1 paper, 2015). "They reported a female term infant with a heterozygous mutation in SFTPC who developed severe respiratory insufficiency at 6 weeks of age." (PMID 26000190, 2015).
secondary pulmonary hypertension (1 paper, 2022). "We presented an 11-month-old girl with surfactant protein C deficiency and secondary pulmonary hypertension, successfully treated with hydroxychloroquine, and provided a detailed discussion of the clinical and diagnostic approach and management." (PMID 36291368, 2022).